RNU6-941P (RNA, U6 small nuclear 941, pseudogene)
Gene: Small nuclear RNA gene on chromosome Y (7,378,672 to 7,378,779, forward strand). Ensembl gene ENSG00000252155.
Homologues: Orthologues: chimpanzee U6 (99% identical), macaque U6 (94% identical), macaque U6 (92% identical), pig U6 (81% identical), dog U6 (81% identical), rat U6 (80% identical), guinea pig U6 (77% identical). Paralogues in human: RNU6-146P (98% identical), RNU6-322P (89% identical), RNU6-15P (86% identical), RNU6-26P (85% identical), RNU6-1 (84% identical), RNU6-1060P (84% identical), RNU6-116P (84% identical), RNU6-1175P (84% identical), RNU6-19P (84% identical), RNU6-2 (84% identical), RNU6-3P (84% identical), RNU6-4P (84% identical), and 1285 more.